FASN (fatty acid synthase)
Diseases named in the same sentence as FASN in open-access papers (continued):
Sharing a sentence is not in itself a finding about the gene and the disease.
varicocele (7 papers, 2020 to 2025). A condition characterized by the dilated tortuous veins of the spermatic cord with a marked left-sided predominance. "Finelli and colleagues reported that patients with varicoceles differentially expressed several key proteins (e.g., fatty acid synthase, myeloperoxidase, or mitochondrial aconitate hydratase) specifically associated with DNA repair." (PMID 38392299, 2024). "We validated ACO2 downregulation (fold change=0.37, change%=-62.7%, P=0.0001) and FASN overexpression (fold change = 4.04, change %= 303.7%, P = 0.014) in men with varicocele compared to controls." (PMID 34975746, 2021). "In particular, we confirmed by WB analysis the altered expression of ACO2 and FASN, which was previously observed by mass spectrometry, and proposed a model linking their differential expression and DNA damage/repair mechanisms in varicocele." (PMID 34975746, 2021). "We identified ACO2 and FASN as possible mediators of DNA repair, whose expression was altered in varicocele." (PMID 34975746, 2021). "They identified mitochondrial aconitate hydratase (ACO2) and fatty acid synthase (FASN) as potential key proteins involved in DNA repair, whose dysregulated expression may contribute to the DNA damage observed in the pathophysiology of varicocele." (PMID 40700278, 2025). "We identified ACO2 and FASN as possible proteins involved in DNA repair, whose altered expression may contribute to DNA damage in varicocele pathophysiology." (PMID 34975746, 2021). "Hence, FASN overexpression in varicocele sperm samples may represent a cellular effort to counterbalance DSB induced by varicocele disease through the activation of the NHEJ pathway." (PMID 34975746, 2021). "Differential expression of the proteins fatty acid synthase (FASN) and mitochondrial ouabain hydratase (ACO2) was found to be involved in DNA damage repair in varicocele semen samples." (PMID 39333437, 2025). "In particular, the analysis showed 2 (FASN, MPO) and 3 (ACO2, NUP93, and PSMD14) proteins, which were significantly over- and under-expressed, respectively (P <0.03) in varicocele samples and reported to be involved in DNA repair function." (PMID 34975746, 2021). "The main protein associated with SDF in patients with varicocele is fatty acid synthase (FASN), which has been proposed as a marker to differentiate samples with high SDF among patients with varicocele." (PMID 33266209, 2020). "Proteins associated with oxidative stress (PRDX2), DNA fragmentation (fatty acid synthase; FASN) and the inflammatory response (FN1) were also overexpressed in the bilateral varicocele group, indicating an increased inflammation and oxidative stress in this group, compared to unilateral varicocele." (PMID 32987677, 2020).
diffuse large B-cell lymphoma (6 papers, 2011 to 2025). "Here, in diffuse large B-cell lymphoma, the authors show that fatty acid synthase increases USP11 interaction with and stability of eIF4B via PI3K-S6Kinase signaling, promoting oncogenic protein translation." (PMID 29483509, 2018). "Based on our literature search, we identified reports describing a high level of FASN expression in myelomas and in diffuse large B-cell lymphomas." (PMID 22485149, 2012). "Given that the overexpressed FASN served as the molecular marker of unfavorable prognosis and malignant progression in multiple cancers, we sought to investigate its potential impact on the development and prognosis of diffuse large B-cell lymphoma (DLBCL)." (PMID 39345091, 2024). "In diffuse large B-cell lymphoma (DLBCL), ZDHHC21 acts as a tumor suppressor by palmitoylating FASN at Cys1317, reducing FASN stability and fatty acid synthesis." (PMID 40977744, 2025).
heart failure (6 papers, 2011 to 2023). Inability of the heart to pump blood at an adequate rate to meet tissue metabolic requirements. "Whole-genome gene expression profiling identified up-regulated heart-failure-related genes such as resistin, adiponectin, and fatty acid synthase, and type 1 and 3 collagens." (PMID 34576047, 2021). "Increased messenger RNA (mRNA) and protein expression of FASN was detected in human heart failure due to ICM, which is inconsistent with our result." (PMID 29361784, 2018). "Apart from over-activation of the adrenergic system, the angiotensin II AT1 receptor, another key player in the development of heart failure, also up-regulates the cardiac fat metabolism by increasing the expression of FASN." (PMID 21711241, 2011). "In agreement with that conclusion, heart biopsy specimens of patients with heart failure showed massive lipid accumulation and high protein levels of key fat metabolizing enzymes FASN, SCD1 and UCP1." (PMID 21711241, 2011). "Immunohistological analysis detected high protein levels of key fat synthesizing enzymes, FASN and SCD1, in the hypertrophic myocardial tissue of patients with heart failure (left)." (PMID 21711241, 2011). "Immunoblot detection was used to quantify protein levels of FASN, SCD1 and UCP1 in cardiac tissue specimens from patients with heart failure." (PMID 21711241, 2011).
hypertriglyceridemia (6 papers, 2014 to 2025). A laboratory test result indicating elevated triglyceride concentration in the blood. "Inhibition of central enzymes such as ACC or FASN can trigger compensatory pathways and, in some settings, hypertriglyceridemia or steatosis, which necessitates careful monitoring and combination strategies." (PMID 41373990, 2025). "Compared with injection of hydrogel-encapsulated T317, the oral administration or injection of free T317 stimulates expression of FASN and SREBP1, thereby inducing de novo fatty acid biosynthesis, fatty liver and hypertriglyceridemia." (PMID 33456564, 2021).
prostate intraepithelial neoplasia (6 papers, 2016 to 2024). A neoplastic proliferation of the epithelial cells that line the acini and the ducts of the prostate gland. "Accordingly, increased de novo lipid synthesis is often detected in PCa where overexpression of lipogenic enzymes such as FASN occurs in both early (prostate intraepithelial neoplasia (PIN)) and late (metastasis) stages of PCa." (PMID 26934656, 2016). "It has been reported that FASN upregulation participated in the progression of PCa, which is the initial event in PCa development and increased substantially from prostatic intraepithelial neoplasia to low grade, to high grade, and to androgen-independent bone metastases." (PMID 32655718, 2020). "In fact, FASN is often overexpressed in both the early (prostatic intraepithelial neoplasia) and late (metastasis) stages of PCa, suggesting that it is involved in the process of the initial phases of prostate tumorigenesis, maintenance, and biological aggressiveness." (PMID 32655718, 2020). "In a high-grade prostate intraepithelial neoplasia mouse model, the overexpression of fatty acid synthase and ABCA1 knockout led to prostate intraepithelial neoplasia progressing to invasive PCa with a 100% penetrance rate." (PMID 39200296, 2024).
acute myeloid leukemia (5 papers, 2020 to 2025). Acute myeloid leukemia (AML) is a group of neoplasms arising from precursor cells committed to the myeloid cell-line differentiation. "In this study, we examined the role of fatty acid synthase (FASN) in c-Kit signaling in both human and murine acute myeloid leukemia (AML) cell lines with activating c-Kit mutations." (PMID 40149597, 2025). "Meanwhile, up-regulation of FASN has been reported in acute myeloid leukemia (AML), mantle cell lymphoma (MCL), and MM." (PMID 36106108, 2022). "We found that FASN mRNA levels were significantly higher in acute myeloid leukemia (AML) patients than in healthy granulocytes or CD34+ hematopoietic progenitors." (PMID 33742137, 2021). "In acute myeloid leukemia (AML), FASN expression is found to be significantly higher in the AML cohort when compared to granulocytes and CD34+ hematopoietic progenitor cells from healthy donors." (PMID 32872164, 2020).
adenoma (5 papers, 2020 to 2024). A neoplasm arising from the epithelium. "Consistently, multi-omics analysis of adenoma tissues showed downregulation of cancer-associated signaling and metabolic pathways due to hetero- and homozygous deletion of FASN in mouse intestinal epithelium cells." (PMID 38732103, 2024). "FASN is highly expressed in endothelial cells, immune cells, and fibroblasts associated with cancer, suggesting the potential impact of FASN expression in these cells on the levels of FAs observed during adenoma formation." (PMID 35742953, 2022). "Western blot analysis on adenoma tissues confirmed that downregulation of FASN leads to a decrease in GFPT1 and OGT protein expression, with a more profound effect on expression of GFPT1." (PMID 38732103, 2024). "Genetic and pharmacological downregulation of FASN in mouse adenoma organoids decreases the activation of β-catenin and expression of Notum and significantly inhibits organoid formation and growth." (PMID 39404424, 2024). "We have shown that FASN is significantly upregulated in Apc-driven adenomas from Apc/Cre mice and promotes adenoma formation in this model." (PMID 38732103, 2024). "In summary, our data suggest that upregulation of FASN during Apc-driven carcinogenesis increases the expression of GFPT1 and OGT and the level of O-linked glycosylation of proteins in intestinal and adenoma tissues." (PMID 38732103, 2024). "We did not address the potential contribution of diet, adipose tissue, or stromal compartment (where the expression of FASN is intact in our mouse model) to the level of FAs or the contribution of metabolites to adenoma tissues and circulation." (PMID 35742953, 2022). "In this study, we noted that heterozygous deletion of FASN in intestinal epithelial cells decreased the levels of several diglycerides in adenomas." (PMID 35742953, 2022). "Immunohistochemistry staining of intestinal tissues from Apc/Villin-Cre (Apc/Cre) mice demonstrates high expression of FASN in adenomas as compared to surrounding tissues." (PMID 35742953, 2022). "We have also analyzed the levels of triglycerides in adenoma tissue and plasma of Apc/Cre, FASN+/∆/Apc/Cre, and FASN∆/∆/Apc/Cre using a triglyceride quantification kit." (PMID 35742953, 2022). "The heat map of the RPPA analysis shows the levels of metabolic enzyme expression in adenomas collected from Apc/Cre, FASN+/∆/Apc/Cre, and FASN∆/∆/Apc/Cre mice." (PMID 35742953, 2022). "Immunohistochemistry staining of FASN and CS revealed that both are significantly upregulated in intestinal epithelium and adenomas in Apc/Cre mice as compared to intestinal tissues of wild-type C57BL/6J mice." (PMID 35742953, 2022). "The PLS-DA further demonstrates a significant difference in the metabolic profiles of adenomas among Apc/Cre, FASN+/∆/Apc/Cre, and FASN∆/∆/Apc/Cre mice." (PMID 35742953, 2022). "To assess FASN-mediated changes of metabolites in glycolysis and the TCA cycle, we performed a metabolic analysis of adenomas from Apc/Cre, FASN+/∆/Apc/Cre, and FASN∆/∆/Apc/Cre mice using GC-MS." (PMID 35742953, 2022). "To determine the effect of FASN on gene expression profile during Apc-driven carcinogenesis, we performed RNA-Seq analysis on adenomas collected from Apc/Cre, FASN+/∆/Apc/Cre and FASN∆/∆/Apc/Cre mice." (PMID 35742953, 2022). "To investigate the contribution of FASN to survival and adenoma formation, we used Apc/Cre and FASN+/∆/Apc/Cre mice kept on standard laboratory chow." (PMID 35742953, 2022). "Strikingly, we observed significant downregulation of this enzyme in adenomas from FASN+/∆/Apc/Cre and FASN∆/∆/Apc/Cre mice as compared to Apc/Cre mice." (PMID 35742953, 2022). "Together, these data suggest that FASN promotes CRC initiation by increasing the number of adenomas formed and the proliferation of CRC cells, thus decreasing mouse survival." (PMID 35742953, 2022).
adenoma (continued). "Our study is the first to elucidate the effect of Villin-Cre-mediated downregulation of FASN expression in intestinal epithelial cells on mice survival, adenoma formation, and transcriptome and metabolome of adenomas in the transgenic model of Apc-driven CRC." (PMID 35742953, 2022). "In summary, these data further confirm that FASN promotes adenoma formation via altered expression of genes involved in proliferation, energy production, and CRC progression." (PMID 35742953, 2022). "Adenoma tissues and plasma from Apc/Cre and FASN+/∆/Apc/Cre mice were analyzed to determine the levels of free fatty acids." (PMID 35742953, 2022). "In summary, we show that an increase in FASN expression during adenoma formation and CRC progression leads to the upregulation of GFPT1 and OGT, as well as an increase in the level of O-GlcNAcylation and, consequently, to enhanced cellular proliferation, tumor growth and metastasis." (PMID 38732103, 2024). "Similarly, FASN was significantly upregulated in mouse adenomas, which is consistent with data from our group and suggest that upregulation of FASN is an early event in Apc-driven CRC." (PMID 38590663, 2024). "Therefore, we measured the total levels of diglycerides and sphingolipids in adenomas from Apc/Cre and FASN+/∆/Apc/Cre mice." (PMID 35742953, 2022). "However, we did not observe any unequivocal changes in the total levels of free fatty acids or sphingolipids in adenomas from mice with heterozygous deletion of FASN." (PMID 35742953, 2022). "The decrease in the levels of glucose in adenomas from FASN+/∆/Apc/Cre and FASN∆/∆/Apc/Cre mice suggests that glycolytic enzymes may be upregulated due to the limited substrate availability." (PMID 35742953, 2022). "Restoration of Nudt7 by tail-vein injection into Nudt7−/− mice significantly reduced the development of adenoma observed in Nudt7−/− mice colons and the number of FABP4-, FASN-, Ki67-, CD45-, and SCD1-positive cells." (PMID 32131398, 2020). "Immunohistochemistry analysis demonstrates that FASN, GFPT1 and OGT are highly expressed in mouse Apc/Cre intestinal adenomas as compared to surrounding normal mucosa and the patterns of FASN and GFPT1 expression are very similar in adenoma tissues." (PMID 38732103, 2024). "Consistently, FASN is significantly overexpressed in rectal biopsies from patients harboring adenomas compared with those with no adenomas." (PMID 35742953, 2022). "We noted that even though the expression pattern of CS does not always recapitulate that of FASN, their expression seems to localize in the same areas of developing adenomas." (PMID 35742953, 2022). "Together, these data suggest that the heterozygous deletion of FASN primarily alters the levels of diglycerides but does not significantly affect the total level of free fatty acids and sphingolipids in mouse adenomas." (PMID 35742953, 2022). "Upregulation of FASN and lipid synthesis is critically important in Apc-driven CRC initiation as it orchestrates changes in the transcriptome, proteome, and metabolic pathways consistent with increased cellular proliferation, ATP production, anabolism, and adenoma formation." (PMID 38590663, 2024). "Interestingly, the levels of diglycerides in adenomas and free fatty acids in adenomas and plasma are not affected by the changes in FASN expression in the intestine." (PMID 35742953, 2022).
autoimmune disease (5 papers, 2020 to 2025). A disorder resulting from loss of function or tissue destruction of an organ or multiple organs, arising from humoral or cellular immune responses of the individual to their own tissue constituents. "In some pathological conditions such as tumors, cardiovascular diseases, inflammatory diseases, and autoimmune diseases, FASN expression and the content of fatty acid products synthesized from FASN are abnormally changed." (PMID 38272906, 2024). "Consequently, FASN contributes to the onset and progression of various conditions, including tumors, cardiovascular diseases, inflammatory diseases, autoimmune diseases, infectious diseases, and other pathological states." (PMID 40332099, 2025). "Indeed, in vivo inhibition of FASN in Th17 cells leads to reduction of autoimmune disease in mice, perhaps reflecting the crucial balance between Tregs and Th17 in preventing autoimmunity." (PMID 34526996, 2021). "Another study also found that the upregulation of FASN expression in Tregs of APS-1, an organ-specific autoimmune disease characterized by single-gene mode inheritance, indicates increased metabolic activity and correlates with functional impairments of Tregs." (PMID 38272906, 2024).
brain tumors (5 papers, 2013 to 2024). "We recently showed that RT promotes FASN-mediated unsaturated fatty acids to protect GBM cells from undergoing apoptosis and sustain their survival, thus further reinforcing the rationale for targeting FASN in irradiated brain tumors." (PMID 38893165, 2024). "For example, overexpression of fatty acid synthase results in enhanced lipogenesis, a common feature in a variety of human cancers, including primary brain tumors; and inhibiting fatty acid synthase or lipogenesis induces cancer cell death." (PMID 24893952, 2014). "We show that in BCBM cells targeting ACSS2 reduces levels of FASN levels thus suggesting that ACSS2 may be an attractive alternative therapeutic strategy for the treatment of lipid-dependent brain tumors." (PMID 38818373, 2024).
colitis (5 papers, 2018 to 2024). Inflammation of the colon. "By immunohistochemistry, we have shown that FASN expression increases in the mucosa in the mice with colitis." (PMID 36266428, 2022). "Moreover, the FASN inhibitor C75 can significantly inhibit the expression of FASN and effectively reduce the severity of experimental colitis by inhibiting dextran sodium sulfate (DSS)-induced activation of the inflammatory pathway." (PMID 38272906, 2024). "Moreover, metformin, a hypoglycemic drug, can improve DSS-induced colitis by blocking the proinflammatory activation of macrophages by inhibiting the FASN/Akt pathway." (PMID 38272906, 2024). "Therefore, these improvements directly showed that metformin or inhibition of FASN ameliorated macrophages-involved colitis." (PMID 34642298, 2021).
esophageal cancer (5 papers, 2021 to 2024). A primary or metastatic malignant neoplasm involving the esophagus. "HNRNPA2B1 can promote the progression of esophageal cancer by up-regulating fatty acid synthase as a carcinogen." (PMID 37074800, 2023). "In esophageal cancer, the role of fatty acid synthase (FASN) has been extensively described and even proposed as a potential therapeutic target." (PMID 36233047, 2022). "Downregulated FASN expression reduced the expansion and migration of esophageal cancer cells and should be considered a therapeutic strategy in esophageal cancer." (PMID 36106333, 2022). "For instance, FASN is expressed at remarkably increased levels in esophageal cancer, and C93 can inhibit the growth of EC." (PMID 36106333, 2022).
malignant meningiomas (5 papers, 2021 to 2025). "In the field of tumor research, SPIRE2 has been proven to interact with miR-195 through the ceRNA mechanism, thereby regulating fatty acid synthase (FASN) and playing a significant role in malignant meningiomas." (PMID 41459538, 2025). "Among the identified genes, FASN stood out, the activity of which is significantly increased in malignant meningioma." (PMID 38577017, 2024). "This study sheds light on the pathogenesis of malignant meningiomas, highlighting the role of FASN and miR-195–5p." (PMID 38577017, 2024).